IGF2BP1 (insulin like growth factor 2 mRNA binding protein 1)
Diseases named in the same sentence as IGF2BP1 in open-access papers (continued):
Sharing a sentence is not in itself a finding about the gene and the disease.
cancer (continued). "However, IGF2BP1 and MYC mRNA expression appear barely correlated in most cancers and IGF2BP1 ablation results in conserved and exclusive impairment of G1/S transition." (PMID 32761127, 2020). "This supported IGF2BP1’s role as a mainly 3′UTR-dependent mRNA-stabilizing mRBP in cancer." (PMID 32761127, 2020). "However, among IGF2BPs, only IGF2BP1 shows strong conservation of oncogenic potential in cancer-derived cell lines." (PMID 32761127, 2020). "In addition, IGF2BP1/2/3 (insulinlike growth factor 2 MRNA-binding protein 1/2/3) exhibited reverse expression pattern in cancer progression, suggesting an oncofetal reprogramming in cancer." (PMID 33575259, 2020). "However, conserved effector pathway(s) and the feasibility of targeting IGF2BP1 in cancer remained elusive." (PMID 32761127, 2020). "However, accumulating evidence has showed that IGF2BP1 was re-expressed in various malignant tumors including HCC, melanoma and rhabdomyosarcomas." (PMID 31427725, 2019). "Moreover, studies have investigated the function of IGF2BP1 in promoting cell proliferation, apoptosis and invasion in various cancers." (PMID 30569605, 2019). "In conclusion, these findings suggested that although IGF2BP1 may have variable regulatory ‘potency’ on specific mRNAs in distinct cancer cells, it serves conserved functions and controls similar pathways at varying extend or significance in these cells." (PMID 30371874, 2019). "Likewise, IGF2BP1 probably influences the MAPK-modulated activity of SRF/TCF-dependent transcriptional control in cancer cells." (PMID 30371874, 2019). "Thus, IGF2BP1 is an attractive target for anti-cancer and anti-drug resistance therapy in clinical practice." (PMID 31427725, 2019). "Therefore, IGF2BP1 has been traditionally regarded as an oncogene and potential therapeutic target for cancers." (PMID 29954406, 2018). "Therefore, more interconnectivity between IGF2BP1 and its targeted mRNAs or ncRNAs can be explored in contexts related to specific cancer conditions." (PMID 29954406, 2018). "Thus, IGF2BP1 is considered to be one of the most promising therapeutic targets for treating cancers, as well as the use of inhibitors of IGF2BP1-mediated cell signaling would emerge as a potential strategy for cancer treatment." (PMID 29954406, 2018). "The bulk of correlative studies describing enhanced expression or de novo synthesis of IGF2BP1 in human cancer and animal model provide strong evidence that IGF2BP1 serves important roles in controlling embryonic development, as well as functions as an oncogenic factor in most of cancers." (PMID 29954406, 2018). "However, it should be noted that the de novo synthesis of IGF2BP3 and to a lesser extent IGF2BP1 have been reported to correlate with enhanced metastasis and poor prognosis in various cancers." (PMID 23069990, 2013). "However, in cancer tissues, IGF2BP1 and IGF2BP3 both tested positive." (PMID 37234166, 2023). "On the other hand, as for cancer, the oncofetal expression pattern of IGF2BP1 could be exploited for developing novel anti-viral therapies, since the depletion/inactivation of this protein in adult tissues should have only little effects on normal cellular physiology." (PMID 37515119, 2023). "To see whether 7773 inhibition of Igf2bp1 affects target RNA levels, we analysed steady state levels of several previously identified, cancer-associated RNA targets in ES2 and H1299 cancer cell lines, which express high levels of Igf2bp1, using quantitative PCR." (PMID 34895045, 2022). "The expression of IGF2BP1 (probe: 227377_at*) was considered as a top-quality cancer biomarker for classifying chemotherapy responsiveness in this cohort at the strong cutoff, suggesting that enhanced IGF2BP1 expression may contribute to therapeutic resistance in CRC subpopulations." (PMID 34203267, 2021).
cancer (continued). "In addition, the findings presented here strongly suggest that the de novo synthesis of IGF2BP1 is further promoted by the downregulation of the let-7 family, supporting a pro-oncogenic, let-7 antagonizing role previously demonstrated for IGF2BP1 in other cancer models." (PMID 34885022, 2021). "However, evaluation of these candidate mRNAs provides strong evidence for the validity of the in silico studies and support the notion that IGF2BP1 is a conserved, post-transcriptional enhancer of pro-oncogenic factors in cancer cells due to primarily 3’UTR dependent stabilization of target mRNAs." (PMID 33829040, 2021). "IGF2BP1 may play a role in cancer by affecting classical oncogenes such as MYC and KRAS." (PMID 34794452, 2021). "In addition, pan-cancer’s risk gene is METTL3 and the protective gene is IGF2BP1." (PMID 34957092, 2021). "In addition to E2F transcription factors, IGF2BP1 also stabilizes E2F-driven transcripts directly indicating post-transcriptional ‘super’-enhancer role of the protein in E2F-driven gene expression in cancer." (PMID 32761127, 2020). "So far, however, only a small number of known cancer-associated lncRNAs have been found to be regulated by the interaction with RBPs like human antigen R (HuR), ARE/poly(U)-binding/degradation factor 1 (AUF1), insulin-like growth factor 2 mRNA-binding protein 1 (IGF2BP1), and tristetraprolin (TTP)." (PMID 32340118, 2020). "We focused on the interconnectivity between IGF2BP1 and its targeted mRNAs or ncRNAs involved in the biological processes of embryogenesis and tumorigenesis, as well as aid in the identification of potential targets for cancer therapy and contribute to the cancer drug-discovery research." (PMID 29954406, 2018). "However, whether LIN28B also induces PARP- and caspase-3-mediated apoptosis in AML and other cancers by downregulating IGF2BP1 is unknown." (PMID 29954406, 2018). "IGF2BP1 may be upregulated as a consequence of mutated FAF1 not being able to suppress WNT signaling in this specific cancer." (PMID 25861239, 2015). "We further confirmed this classification by calculating the average expression of IGF2BP1, IGF2BP2, and IGF2BP3 across cancer types and clusters, which consistently showed the highest levels in IGF2BP-H, intermediate in IGF2BP-M, and lowest in IGF2BP-L." (PMID 41049442, 2025). "IGF2BP1, IGF2BP2, and IGF2BP3 were upregulated in the SCAN-B cohort, aligning with their widespread dysregulation in cancer." (PMID 40918643, 2025). "IGF2BP1 can also affect the stability of ITGB1 mRNA through m6A modification to promote its translation and facilitate cancer cell metastasis and drug resistance." (PMID 41280724, 2025). "IGF2BPs, particularly IGF2BP1 and IGF2BP3, are oncofetal proteins and exhibit significantly up-regulated expression and prognostic correlation in various human cancers." (PMID 37280679, 2023). "IGF2BP1, an oncofetal RNA binding protein (RBP), is known to be overexpressed in several cancers including B-ALL." (PMID 37670323, 2023). "Recent, pre-clinical evidence indicates the feasibility of direct and indirect targeting of IGF2BP1 and MYCN in cancer treatment." (PMID 37246217, 2023). "Collectively, these findings demonstrate a broad, complex mechanism of action for IGF2BP1, SH3PXD2A-AS1, and their target mRNAs in promoting the cancer cell cycle." (PMID 37537521, 2023). "Hence, IGF2BP1 may have great potential in cancer treatment." (PMID 36632449, 2023). "We believe that the cancer-promoting role of ECE2 gene is related to the modification of m6A, which may affect the methylation level of LUAD, especially HNRNPC, through its association with HNRNPC, IGF2BP1, IGF2BP3 or RBM15, and ultimately affect the progression of LUAD." (PMID 36299451, 2022).
cancer (continued). "All human IGF2BPs have been identified as oncofetal proteins, and among them, IGF2BP1 and IGF2BP3 are bona fide oncofetal proteins that are synthesized in many cancers." (PMID 35541906, 2022). "Real-time polymerase chain reaction, Western blot, and immunohistochemistry were performed to detect the mRNA and protein level of IGF2BP1 in LUAD tissues and para-carcinoma tissues." (PMID 36249006, 2022). "Among them, there were 12 m6A regulatory genes, including IGF2BP1, with a significantly higher expression in LUAD tissues compared with para-carcinoma tissues, while FTO, METTL14, WTAP, and ZC3H13 showed a significantly lower expression." (PMID 36249006, 2022). "To prove the validity of these in silico evaluations, we validate three novel target mRNAs by demonstrating that IGF2BP1 promotes the expression of AURKA, HDLBP, and YWHAZ in cancer cells by impairing decay of the respective mRNAs." (PMID 33829040, 2021). "Mimicking Lnc-THOR depletion-induced anti-cancer activity, CRISPR/Cas9-induced IGF2BP1 KO potently inhibited NSCLC cell proliferation and migration." (PMID 34868966, 2021). "By searching the GSCALite database, we found that the expressions of many m6A methylation regulators (especially IGF2BP1, IGF2BP2, and IGF2BP3) were changed across multiple cancer types." (PMID 35003212, 2021). "Together with IGF2BP1, IGF2BP3 facilitates invadopodia formation and cancer metastasis by preventing the degradation of the CD44 mRNA." (PMID 34203267, 2021). "The results suggested that the SNVs of the 20 m6A regulators altered in 74.8% TCGA samples across cancer types, and the waterfall plots presented the top ten SNVs-changed genes, such ZC3H13, YTHDC2, and IGF2BP1." (PMID 35003212, 2021). "This supported prior findings demonstrating, for instance, that the downregulation of the let-7 miRNA family promotes the upregulation of IGF2BP1 and RRM2 in cancer." (PMID 34885022, 2021). "As evidence has shown important roles of IGF2BP1, IGF2BP2, and IGF2BP3 in cancer, we next explored their expression in various types of cancer." (PMID 33575259, 2020). "For the three selected regulators, IGF2BP1, VIRMA, and ZC3H13, the GSEA study result indicated that they were also all correlated with pathways in cancer and WNT signaling pathways." (PMID 32950970, 2020). "Here, we reveal that IGF2BP1 stabilizes E2F1–3 mRNAs leading to enhanced E2F-driven gene expression and cell cycle progression in cancer cells." (PMID 32761127, 2020). "IGF2BP1 can increase the stability of CD44 mRNA and promotes cell adhesion and invadopodia formation in cancer cells." (PMID 31897227, 2020). "As expected, silencing of IGF2BP1 suppressed CRC cell proliferation, colony formation, migration, and invasion in HCT-116 and SW480 CRC cells, similar to the cancer phenotypes induced by RBRP knockdown." (PMID 32245947, 2020). "IGF2BP1 stabilizes the CD44 mRNA through binding to its 3′-UTR, and thereby contributes to cellular adhesion and invasion during cancer development and formation." (PMID 32967226, 2020). "Our studies reveal that IGF2BP1 is the first RBP acting as a conserved post-transcriptional enhancer of E2F-driven gene expression and G1/S-transition in cancer cells and tumors." (PMID 32761127, 2020). "The small molecule BTYNB was reported to inhibit IGF2BP1 from binding to c-MYC mRNA and showed moderate cytotoxic effects in various cancer-derived cells." (PMID 32545414, 2020). "Taken together, this suggests that IGF2BP1 promotes SRF-dependent transcription in a largely miRNome- and potentially m6A-dependent manner in cancer." (PMID 30371874, 2019). "This anti-cancer activity is attributed to suppression of lncRNA THOR, followed by downregulation of IGF2BP1 mRNA targets involving Myc, IGF2, and Gli1." (PMID 31178721, 2019). "The oncofetal mRNA-binding protein IGF2BP1 and the transcriptional regulator SRF modulate gene expression in cancer." (PMID 30371874, 2019).
cancer (continued). "With regard to TP, PTEN is an important target; while TN possesses anti-cancer activity in vitro and in vivo through regulating lncRNA THOR/IGF2BP1 signaling." (PMID 31178721, 2019). "If the SRF/IGF2BP1-dependent enhancement of FOXK1 and PDLIM7 has prognostic value in cancer, it was evaluated by Kaplan–Meier analyses using KM plotter." (PMID 30371874, 2019). "IGF2BP1 and IGF2BP3 have been reported in multiple types of cancers as stability regulators of multiple mRNAs." (PMID 29679004, 2018). "The IGF2 mRNA binding protein family (IGF2BPs) is comprised of three members: IGF2BP1, IGF2BP2, and IGF2BP3, which are bona fide oncofetal proteins involved in various human cancers." (PMID 26547929, 2015). "Despite controversial observations regarding a potential involvement of IGF2BPs in metastasis, IGF2BP1 and IGF2BP3 emerge as potent modulators of cell migration during development and in cancer." (PMID 23069990, 2013). "However, abnormal expression of IGF2BP2 and reactivation of IGF2BP1 and IGF2BP3 are frequently observed during cancer progression." (PMID 41049442, 2025). "Unlike other p38 MAPK substrates, IGF2BP1 is a cancerous fetal protein that is only expressed in cancer cells and will be a potential target for the development of new cancer drugs with fewer side effects." (PMID 40919129, 2025). "Our subgrouping analysis based on 25 m6A-associated genes revealed distinct m6A regulation-driven subgroups in six cancers, with IGF2BP family members (IGF2BP1, IGF2BP2, IGF2BP3; all known m6A readers) emerging as a central factor distinguishing these subgroups." (PMID 41049442, 2025). "Here the authors show that the binding of IGF2BP1-3, especially IGF2BP3, with m7G, could promote the degradation of m7G target transcripts in cancer cells." (PMID 39198433, 2024). "YTHDF1 was highly expressed in cancer cells, while IGF2BP1 did not exhibit statistically significant differences." (PMID 39185313, 2024). "IGF2BP1 and IGF2BP3 are re-expressed in many types of tumors, and IGF2BP2 was also found to be excessively expressed in malignancies due to genomic amplification according to pan-cancer analysis with TCGA data." (PMID 37644505, 2023). "Though several substrates of IGF2BP1 and IGF2BP3 are known in cancers, including ESCC, the downstream mRNAs regulated by IGF2BP2 are largely unknown." (PMID 37444412, 2023). "The RNA-binding protein IGF2BP1 is a transcriptional target of Wnt/β-catenin signaling, normally expressed during development and often reactivated in cancer cells, where it regulates the stability of oncogenic mRNA." (PMID 37829185, 2023). "Therefore, circRRM2/IGF2BP1/MYC formed a positive feedback loop and facilitated the invasion behavior of cancer cells." (PMID 36966311, 2023). "Finally, for IGF2BP1, the oncofetal IGF2 mRNA binding proteins (IGFBPs) are upregulated in various cancer entities and have been shown to possess a distinct conservation of highly oncogenic potential throughout a panel of five cancer-derived cell lines." (PMID 37885041, 2023). "IGF2BP1 is a substrate of the E3 ligase adaptor FBXO45 and potential cancer therapeutic target." (PMID 36293188, 2022). "For example, one study in hepatocellular carcinoma found that IGF2BP1 was able to combine with LIN28B-AS1 to promote the stability and translation of MYC mRNA in an m6A-modification-dependent manner, boosting the proliferation and invasion of cancer cells." (PMID 36249006, 2022). "In this study, IGF2BP1 and 3 are either absent or expressed at very low levels in most normal tissues and cancer cell lines." (PMID 36686749, 2022). "Finally, RT-PCR and WB showed that CDH17, IGF2BP1, IGFBP1, ABCC2, and HMGA2 were differently expressed between human lung fibroblast (HLF) cells and cancer cells." (PMID 35903696, 2022). "In contrast, ZC3H13, IGF2BP1, WTAP, FTO, and YTHDC2 were downregulated in ≥four cancer types." (PMID 35211628, 2022).
cancer (continued). "Interestingly, the expression of IGF2BP1 and IGF2BP3 increased more than twofold in most cancer types." (PMID 35794212, 2022). "Insulin-like growth factor-2 mRNA-binding proteins (IGF2BPs), IGF2BP1 and IGF2BP3, are evolutionarily conserved families of RNA-binding proteins that regulate important parts of cancer cells and promote the development of cancers." (PMID 36727069, 2022). "As bioinformatic analysis and literature reviews indicated that IGF2BP1 is a plausible target for further research, Western blot, immunohistochemistry, and RT-qPCR were carried out to evaluate the IGF2BP1 mRNA and protein levels in the LUAD tissues and para-carcinoma tissues." (PMID 36249006, 2022). "The expression of IGF2BP1/2/3 was significantly reduced in m6ACluster B, which revealed that IGFBP1/2/3 may play a vital role in cancer development." (PMID 34733275, 2021). "This provides strong evidence that IGF2BP1 may further enhance miRNA-dependent regulation in ATC, since the main, conserved role of IGF2BP1 in cancer is the enhancement of pro-oncogenic factors by impairing their miRNA-directed inhibition." (PMID 34885022, 2021). "Although not comprised in any cancer hallmark gene set, we decided to evaluate regulation of HDLBP expression by IGF2BP1 and confirmed that IGF2BP1 promotes HDLBP expression by mRNA stabilization." (PMID 33829040, 2021). "IGF2BP1, together with IGF2BP2 and IGF2BP3, belongs to a family of RBPs that is expressed in embryonic tissue and frequently reactivated in different types of cancers but rarely expressed in normal adult tissue." (PMID 32340118, 2020). "A large proportion (47 RBPs) are commonly regulated in both RSCC and LSCC with several enriched for binding among DEGs (adj p < 0.05), including RBPs previously discussed in the context of CRC such MSI2, MEX3A, IGF2BP1/3, ELVAL4, and cancers in general, such as RBM47, DKC1, CELF4, ELAVL3." (PMID 32293332, 2020). "As shown by the colony formation and MTT assay results, overexpressing circXPO1 in A549 cells stimulated cancer cell proliferation, and the proliferative advantage conferred by circXPO1 overexpression was partially reversed by CTNNB1 silencing and IGF2BP1 silencing." (PMID 33268793, 2020). "This IGF2BP1-driven shortening of the G1 cell cycle phase relies on 3′UTR-, miRNA- and m6A-dependent regulation and suggests enhancement of cell cycle progression by m6A-modifications across cancers." (PMID 32761127, 2020). "Here, we demonstrate that IGF2BP1 promotes SRF and SRF target genes at the post-transcriptional level suggesting it as a post-transcriptional enhancer of SRF itself as well as SRF-dependent gene expression in cancer cells." (PMID 30371874, 2019). "miR-1275, prevalent frequently in various cancers, could hinder HCC cell growth partially by simultaneously regulating the oncogenic IGF2BP1–3 and IGF1R." (PMID 29954406, 2018). "Moreover, it also selectively reduces the levels of other cancer-related IGF2BP1 mRNA targets including CALM1, CDC34, COL5A, and BTRC, similar to the effect by RNAi knockdown of IGF2BP1 both in IGROV-1 and SK-MEL2 cancer cells." (PMID 29954406, 2018). "A loss of FAF1 function could cause constitutive WNT pathway activity (consistent with the downstream inductions of IGF2BP1 and E2F1 in this cancer)." (PMID 25861239, 2015). "IGF2BP1 and IGF2BP3 have been found to be re-expressed in several aggressive cancer types." (PMID 23069990, 2013). "For example, even though there is a large body of in vitro evidence for IGF2BP1 in promoting cell movement, the significance of IGF2BP1 in the process of cancer metastasis has not been directly confirmed through in vivo studies." (PMID 23069990, 2013). "The remaining nine class I peptides were reference peptides, eight of which originated from six genes (MAGEA3, MAGEA6, BRDT, DAZ1, KCNU1, and IGF2BP1) that are expressed in testis but absent from oGTEx and mTECs, with some already known as cancer/testis (C/T) antigens." (PMID 41437377, 2025).